EGFR (epidermal growth factor receptor)
Diseases named in the same sentence as EGFR in open-access papers (continued):
Sharing a sentence is not in itself a finding about the gene and the disease.
cancer (continued). "Epidermal growth factor receptor blockade by monoclonal antibodies or small molecule TK inhibitors (TKIs), such as gefitinib or erlotinib, has now entered clinical practice in patients affected by different types of cancer." (PMID 18665191, 2008). "Most of the cancer specimens had positive staining for Id-1, EGFR and VEGF." (PMID 19014499, 2008). "Indeed, zalutumumab, displaying novel modes of action that distinguish it from other EGFR antibodies, has potential as effective treatment in a variety of cancers." (PMID 18702090, 2008). "Inappropriate signalling through the EGFR and ErbB2/HER2 members of the epidermal growth factor family of receptor tyrosine kinases is well recognised as being causally linked to a variety of cancers." (PMID 18841159, 2008). "However, when inappropriately controlled, due to EGFR overexpression or hyperactivation, these signaling events are characteristic of many cancers." (PMID 21892266, 2008). "Since then, the EGFR has been a major molecular target in the treatment of cancer." (PMID 21892266, 2008). "There have been many studies showing a relationship between Id-1 and EGFR in many types of cancer." (PMID 19014499, 2008). "This hypermethylation, along with the repressed EGFR expression that we observe in the 468LN cells, is somewhat paradoxical in that EGFR expression (a known oncogenic characteristic of cancer cells) has apparently been selected against in the more metastatic 468LN cell line." (PMID 18638373, 2008). "The EGFR antibody also appears to be effective in only a proportion of cancer patients." (PMID 18349843, 2008). "The epidermal growth factor receptor (EGFR) family of receptor tyrosine kinases, which consists of EGFR, ErbB2, ErbB3, and ErbB4, is important in many normal developmental processes and is often over-expressed or mutated in human cancer." (PMID 19019207, 2008). "The hypothesized link between EGFR and cancer was strengthened when in vitro studies showed infection of NIH-3T3 cells with either retrovirus encoding EGFR, or a eukaryotic vector encoding EGFR cDNA, induced a transformed phenotype." (PMID 21892266, 2008). "To investigate the functional consequences of the observed TNK2/EGFR interaction, we wanted to examine how EGFR dynamics might be affected in cancer cells in which TNK2 had been silenced by siRNA treatment." (PMID 18435854, 2008). "Regardless of the cause, increased EGFR activity serves both as a biomarker in the diagnosis of some cancers and is a molecular target for anti-cancer therapies." (PMID 21892266, 2008). "Therefore, over 20 years ago, EGFR signaling inhibition was proposed as a target for cancer therapy." (PMID 18519000, 2008). "Additionally, mutant forms of EGFR and overexpression of EGFR ligands have been recognized to promote cancer progression in a range of solid tumors." (PMID 18702090, 2008). "Cortactin overexpression was associated with significantly increased local recurrence rates (49 vs 28% for high and low expressing carcinomas, respectively), decreased disease-free survival (17 vs 61%), and decreased the 5-year overall survival of (21 vs 58%), independently of the EGFR status." (PMID 18268492, 2008). "The wide range of EGFR expression (14% to 91%) may be accounted for by use of different methods and different criteria for assessment, as well by the presence of basal-like carcinomas that consistently over-express EGFR." (PMID 18522728, 2008). "Moreover, A431 cells are a well established model in EGFR research, and the A549 cells are from a common cancer type in which the effects of Gefitinib have been evaluated in clinical trials." (PMID 17211472, 2007). "Three highly complementary studies published in this issue of PLoS Medicine address this important question and identify the proapoptotic molecule BIM (BCL2-interacting mediator of cell death, also called BCL2-like 11) as critical mediator of EGFR TKI-induced cell death in EGFR-driven cancer." (PMID 17973575, 2007).
cancer (continued). "Almost recently, novel targeted therapeutic strategies including anti-EGFR agents, such as monoclonal antibodies (cetuximab) and small molecules (gefitinib, erlotinib) have been approved for the treatment in some types of EGFR-dependent cancers, such as colon or lung and pancreatic." (PMID 19455247, 2007). "We conducted a feasibility study to examine whether small numbers of cancer cells could be utilised for analysis of the EGFR gene status using the loop-hybrid mobility shift assay, which is a modified heteroduplex technique." (PMID 17047654, 2006). "Together, these reports suggest that nuclear EGFR may play a potential important role in the aggressive biology of cancers, radiosensitivity and clinical outcomes." (PMID 16434982, 2006). "As a number of other receptor tyrosine kinases (RTKs) and cytokine receptors also undergo similar nuclear translocalization, a better understanding of the physiological and malignant nature of the nuclear EGFR pathway will likely shed light into the biology of cancer with nuclear RTKs." (PMID 16434982, 2006). "Inhibition of EGFR in combination with radiotherapy may have therapeutic potential in a range of cancers characterised by EGFR overexpression." (PMID 21614218, 2006). "Preclinical studies in tissue culture and in xenografts using cancer cell lines with known EGFR expression have shown that EGFR overexpression itself might not be a useful predictive marker for response to EGFR targeted therapy." (PMID 16622439, 2006). "For instance, it is yet to be determined whether nuclear EGFR plays a crucial role in the genesis, progression, metastatic growth and/or therapeutic responses of human cancers." (PMID 16434982, 2006). "Overexpression of the EGFR gene significantly enhanced the cells drug resistance, suggesting that EGFR may be one of the contributing factors that affect drug resistance of cancer cells." (PMID 15655552, 2005). "Gefitinib (‘Iressa’, ZD1839 (‘Iressa’ is a trademark of the AstraZeneca group of companies)), an EGFR tyrosine kinase inhibitor, exhibits a broad antitumour spectrum against human cancers in vitro and demonstrated therapeutic benefit in patients with non-small-cell lung cancer." (PMID 15841081, 2005). "The authors found significantly higher EGFR levels in stage III cancers than in stages I and II." (PMID 15967033, 2005). "Among them, the EGFR pathways attracted the most attention of cancer investigators." (PMID 15967033, 2005). "In all, 73 patients (68.2%) displayed a moderate to intense expression of EGFR in cancer cells." (PMID 15986037, 2005). "An immunocytochemistry approach using phospho- and pan-specific EGFR antibodies strengthened the argument for the use of the AP-1-bla ME180 cell line as a viable model for the analysis of a combinatorial targeted agent approach to cancer-related pathways." (PMID 16202132, 2005). "Various strategies have been developed to target EGFR and to deter cancer cell growth." (PMID 15655552, 2005). "ZD1839, a synthetic anilinoquinazoline, is an orally active, highly selective EGFR tyrosine kinase inhibitor (EGFR-TKI) that inhibits ligand-stimulated EGFR autophosphorylation and signal transduction pathways implicated in the promotion of cancer cell growth and proliferation." (PMID 15611794, 2005). "In the pharmacokinetic phase I study in cancer patients, quercetin was well tolerated, and there was evidence of pharmacodynamic activity as indicated by inhibition of epidermal growth factor receptor phosphorylation, yet indications of nephrotoxicity were also observed." (PMID 15292928, 2004). "We first investigated whether IgG reactive to each of the 29 different EGFR-derived peptides could be detected in the sera of 20 cancer patients and 11 HDs." (PMID 15083186, 2004). "Epidermal growth factor receptor-targeted agents have been investigated in several human cancers." (PMID 14760365, 2004).
cancer (continued). "Therefore, from the viewpoint of development of peptide-based cancer therapy, this study was intended to determine the EGFR-derived peptides recognised by both cellular and humoral immunities in HLA-A2+ epithelial cancer patients." (PMID 15083186, 2004). "We urgently need a more comprehensive understanding of the role of EGFR in human cancer." (PMID 15150574, 2004). "Cultures of human carcinoma A-431, A-549 and HeLa cells were challenged with γ-rays without or with concomitant exposure to gefitinib, a potent inhibitor of the tyrosine kinase activity of epidermal growth factor receptor (EGFR)." (PMID 15545965, 2004). "Expression or overexpression of EGFR is frequently observed in human cancers including non-small cell lung cancer and hormone-refractory prostate cancer, and over expression has been associated with poor prognosis in several cancer types, including breast, pancreas and laryngeal." (PMID 11953865, 2002). "All but one of the EGFR positive malignant tumours showed coexpression of IL-4 receptor." (PMID 1419612, 1992). "Expression of EGFR was found in 14/20 polyps and in 22/45 carcinomas." (PMID 1419612, 1992). "Tamoxifen therapy (40 mg d-1) did not influence the expression of PgR, EGFR or Ki67 immunostaining in cancer associated normal tissue (n = 17)." (PMID 1911227, 1991). "Other clinical factors like gender, age, smoking, and alcohol consumption did not demonstrate a significant relationship with EGFR mutation status (p > 0.05), highlighting that the most important predictors of mutation status are cancer stage and treatment type." (PMID 40502411, 2025). "Moreover, activation of EGFR signaling has been shown to elevate Vcam1 levels in cancer cells." (PMID 40683857, 2025). "Moreover, the identification of compounds with dual LSD1/EGFR inhibitory activity provides new insights into the development of more effective cancer treatments, particularly for cases where single-target therapies have shown limited efficacy or led to resistance." (PMID 39753983, 2025). "Therapeutic relevance: Targeting the EGFR-AKT-TSPAN8-STAT3 axis may benefit refractory cancers." (PMID 40977744, 2025). "However, its frequent co-expression with EGFR across various cancer types may contribute to its designation as a positive predictor." (PMID 39995668, 2025). "Notably, we got interested in AKT1 and EGFR due to their role in cancer development." (PMID 40991529, 2025). "The high mutation frequency of EGFR in various human cancers inspired the hypothesis that EGFR could serve as a potential biomarker; however, the deterministic interaction relationship and mechanism between EGFR and TIME has not been fully reported." (PMID 40574864, 2025). "Thus, hyperoside effectively inhibits cancer cell proliferation by lowering EGFR levels." (PMID 40098612, 2025). "Therefore, this QD-based Nb-conjugated micelle may function as a prominent theranostic nanoplatform for EGFR-overexpressing cancers such as TNBCs." (PMID 41304734, 2025). "However, to date, EGFR is the only cancer cell target approved for clinical use in NIR-PIT." (PMID 40792441, 2025). "Thus, the removal of TMED2 results in EGFR degradation, reducing cancer cell proliferation." (PMID 40497947, 2025). "Hence, the suppression of EGFR and Src is one of the most significant targets in cancer treatment." (PMID 41200137, 2025). "Interestingly, crosstalk between EphB6 and EGFR cooperates in cancer progression." (PMID 40065768, 2025). "However, future research should further investigate potential disparities in skin toxicity profiles across different cancers, which may arise from variations in the types of EGFR inhibitors, combination regimens, and patient baseline characteristics." (PMID 41377804, 2025). "Therefore, EGFR is one of the most promising and challenging targets for addressing cancer." (PMID 40535810, 2025).
cancer (continued). "Furthermore, EGFR mutations may lead to increased auto-phosphorylation and MAPK signaling in certain cancers, such as NSCLC, displaying abnormal ubiquitination." (PMID 40210802, 2025). "Activating EGFR mutations could transcriptionally increase CD47 expression via the activation of ERK/c‐Myc and AKT/NF‐κB signaling, which impairs macrophage phagocytosis and mediates innate immune evasion of cancer cells." (PMID 40859900, 2025). "In addition, although most patients respond to EGFR-TKI treatment, the duration of the response is inconsistent between individual cases, and it is expected that pre-existing genetic abnormalities in cancer cells may affect the outcome of EGFR-TKI treatment." (PMID 40136696, 2025). "Moreover, miR-145 may inhibit cancer cell proliferation by targeting genes associated with growth factors, including IRS-1, IGF-IR, or epidermal growth factor receptor (EGFR)." (PMID 39896297, 2025). "Drug resistance and adverse effects are serious issues in the treatment of cancer since intrinsic or acquired resistance often requires modification or even termination of therapeutic approaches including treatment with platinum(ii) complexes and EGFR inhibitors." (PMID 39801772, 2025). "Consequently, EGFR signaling remains active, promoting cancer cell survival and proliferation." (PMID 40141140, 2025). "Together, our data indicate that sorafenib can effectively prevent the emergence of resistance in cancer cells addicted to mutant EGFR, but not in cells addicted to other driver mutations frequently found in NSCLC, such as those involving the oncogenes KRAS and ALK." (PMID 40846697, 2025). "A consensus panel of genes derived from EGFR-associated progression pathways (e.g. fDEGs, invGRN, EGFR-related EMT) represents a promising predictive marker but cannot be assessed using sub-genomic panel sequencing, the current standard in routine molecular diagnostics for cancer patients." (PMID 40121428, 2025). "Tumors arising from EGFR-low cells had a stronger fibrotic phenotype than EGFR-high tumors, and the fibers were highly positive for SMA, suggesting that the EGFR-low tumors were more EMT-like, but also potentially harboring more cancer-associated fibroblasts (CAFs)." (PMID 39747003, 2025). "Alternatively, chromosomally unstable cancer cells may become refractory to EGFR-TKIs." (PMID 40136696, 2025). "Thus, elucidating the regulatory mechanisms governing the EZRIN/EGFR axis and its link with mitochondrial metabolism could suggest novel therapeutic strategies, particularly in the context of cancer." (PMID 41145430, 2025). "Therefore, suppressing AREG activity may be critical for mitigating fibrosis in EGFR inhibitor-treated cancer patients, as indicated by studies in multiple tissue contexts." (PMID 40725192, 2025). "Notably, overexpression of EGFR often promotes the proliferation of cancer cells." (PMID 40098612, 2025). "Furthermore, effective virtual screening across a range of active compounds sourced from different databases, the discovery of potential EGFR inhibitors could lead to novel predictive strategies in the cure of cancer." (PMID 40344575, 2025). "Furthermore, hub genes like EGFR and IL6, already implicated in other cancers, may also represent druggable targets in VS that warrant further validation." (PMID 41231782, 2025). "Several receptors are overexpressed or specifically expressed in different types of cancer, such as folate receptors, integrins, transferrin receptors, G protein-coupled receptors, sigma receptors, fibroblast growth factors and epidermal growth factor receptor (EGFR)." (PMID 39940134, 2025). "Furthermore, we extensively investigated and verified the predictive effectiveness of EGFR.Sig for immunotherapy response and identified hub genes in EGFR.Sig (Hub-EGFR.Sig) with the help of multiple machine learning (ML) algorithms to explore the relationship between EGFR and cancer prognosis." (PMID 40574864, 2025).
cancer (continued). "Furthermore, the Dermatology Life Quality Index (DLQI), Skindex series scales, and the Functional Assessment of Cancer Therapy-Epidermal Growth Factor Receptor Inhibitor-18 (FACT-EGFRIs-18) scale are all patient-reported tools and belong to skin-related quality-of-life scales." (PMID 41377804, 2025). "Therefore, DC‐2 might be worth to be developed further in this cancer‐related context including cancers that are resistant to EGFR therapy." (PMID 40205982, 2025). "This suggests that Cys307 plays a crucial role in EGFR activation and dimerization through redox regulation, and its disruption in the EGFRvIII mutant may contribute to oncogenic signalling, highlighting its potential as a therapeutic target in redox-driven EGFR activation and cancer progression." (PMID 40298862, 2025). "While several studies have indicated that Quercetin downregulates EGFR expression, thereby impeding cancer cell proliferation, some evidence suggests that Quercetin may also activate specific phosphorylation sites (such as Tyr1068) on EGFR, potentially diminishing its anticancer efficacy." (PMID 40218878, 2025). "In addition, various immune cells in the TIME, such as CD4 memory T cells, M2 macrophages and resting mast cells, were negatively correlated with Hub-EGFR.Sig in most types of cancer, while follicular helper T cells, active mast cells, eosinophils and plasma cells were positively correlated." (PMID 40574864, 2025). "Cancer cells harboring the KRAS G12C mutation entered a quiescent state, in which some of the cells died, while others were able to overcome this inhibition through the synthesis of new KRAS G12C proteins that can be rapidly activated through the upstream effectors EGFR and AURKA." (PMID 40597785, 2025). "Similarly, ITH was positively correlated with EGFR.Sig in pan-cancer (R = 0.42, P = 0.021)." (PMID 40574864, 2025). "While the effects of EGF on RPE glucose metabolism are unlikely to be as severe as in EGFR-mutated cancer cells, upregulated EGF in the RPE/choroid during aging and AMD may work to increase glycolysis as seen in other non-cancerous cells." (PMID 39433211, 2025). "While no tumorigenic effects were observed in our study, EGFR is an oncogene that may interact with other genes to influence cancer risk, as oncogenic transformation typically involves multiple genetic and environmental factors." (PMID 41227364, 2025). "Thus, we aimed to investigate whether the ZNF662-NGF axis could modulate the sensitivity of TNBC cells to anti-cancer drugs, particularly EGFR inhibitors." (PMID 40612670, 2025). "Additionally, the role of p66Shc in modulating survival pathways may have broader implications for NSC-like cancers, where assessing p66Shc levels could provide prognostic value for the sensitivity of cancers to EGFR- or MEK-inhibition-based chemotherapies." (PMID 40593476, 2025). "This review presents an overview of the role and current landscape of EGFR inhibitors in cancer treatment, with a particular emphasis on recent progress in the design, synthesis, and development of novel thiazole hybrid compounds as promising selective EGFR TKIs." (PMID 41488515, 2025). "Therefore, combining EGFR-TKIs with another treatment modality may inhibit the cancer sub-clones resistant to EGFR-TKIs." (PMID 40191716, 2025). "The observation of heightened EGFR expression in cancer cells, coupled with the established correlation between EGFR overexpression and reduced patient survival, has spurred the development of numerous therapeutic strategies aimed at specifically targeting EGFR." (PMID 39816681, 2025). "Furthermore, next-generation sequencing (NGS) was performed using tissue sample (tumor cellularity 70%, including 168 cancer-related genes; Burning Rock, Beijing, China) showed EGFR exon 19 p.E746_S752delinsV in-frame deletion (frequency as 30.67%) caused by c.2237_2255delinsT mutation." (PMID 40365349, 2025).